RAB3A (RAB3A, member RAS oncogene family)
Diseases named in the same sentence as RAB3A in open-access papers (continued):
Sharing a sentence is not in itself a finding about the gene and the disease.
epilepsy (1 paper, 2021). A brain disorder characterized by episodes of abnormally increased neuronal discharge resulting in transient episodes of sensory or motor neurological dysfunction, or psychic dysfunction. "RAB3A deficiency can regulate epilepsy and synaptic activity in hippocampal CA1 region by impair excitatory glutamate synaptic transmission and synaptophysin II synergism." (PMID 34422904, 2021).
haemorrhoid (1 paper, 2020). "However, the results showed that the expression levels of all important node genes (CLTA, CLTC, RAB3A, SNAP25, SYT1, VAMP2) on Synaptic vesicle cycle pathways from haemorrhoid patient samples were lower significantly than them from healthy tissue samples." (PMID 32620169, 2020).
Huntington chorea (1 paper, 2017). "For example, increased RPH3A, Ras-related protein Rab-3A promotes synaptic vesicle traffic and fusion while aberrant interaction with alpha-synuclein leads to aggregates found in Huntington chorea." (PMID 28423529, 2017).
insulinoma (1 paper, 2024). "The transfection of insulinoma cells with constitutively active Rab3a inhibited insulin release, indicating that continuous insulin secretion seems to demand the rapid cycling of Rab3a between an active and inactive state." (PMID 38999937, 2024).
lung fibrosis (1 paper, 2024). "Therefore, RAB3A may participate in EMT progression through TGF-β signaling in lung fibrosis." (PMID 38612561, 2024).
non-small cell lung carcinoma (1 paper, 2025). A group of at least three distinct histological types of lung cancer, including non-small cell squamous cell carcinoma, adenocarcinoma, and large cell carcinoma. "Together these results suggest that RAB3A mediates the transport of BAG6 to mitochondria, thereby optimizing the therapeutic potential of cisplatin for non-small cell lung cancer treatment." (PMID 41123819, 2025).
pancreatic ductal adenocarcinoma (1 paper, 2022). An infiltrating adenocarcinoma that arises from the epithelial cells of the pancreas. "Supporting this notion, though RAB3A mRNA could be detected, a lack of RAB3A immunostaining in pancreatic ductal adenocarcinoma (PDAC) tissues were reported." (PMID 35154286, 2022).
Spastic paraplegia (1 paper, 2023). Complete loss of the ability to move the lower limbs accompanied by spasticity of the lower limbs. "RAB3A is listed as a candidate gene for a familial form of spastic paraplegia." (PMID 37510383, 2023).
tumor (10 papers, 2017 to 2025). "The overexpression of HSPA1A, CD99 and RAB3A showed to be associated with advanced tumour stage, tumour type II, tumour progression, and primary chemotherapy resistance." (PMID 33686173, 2021). "The result showed that RAB3A knockdown enhances the ability of cisplatin to inhibit tumor cell proliferation." (PMID 41123819, 2025). "Conversely, RAB3A overexpression augmented mitophagy, ultimately enhancing tumor cells’ tolerance to oxidative stress." (PMID 41123819, 2025). "To further establish how RAB3A promotes tumor growth, we conducted a protein mass spectrometry experiment (MS) for examining the interaction between RAB3A and specific molecules." (PMID 41123819, 2025). "In a similar manner, our results showed that the overexpression of RAB3A associated with shorter OS, PFS, and poorer prognosis, including tumour type and cisplatin-based therapy resistance." (PMID 33686173, 2021). "Since HCC tumors are commonly hyper O-GlcNAcylated, the tumor-suppressive function of Rab3A is likely diminished in HCC." (PMID 33747521, 2021). "Key tumorigenic molecules contained in the Synaptic vesicle cycle pathway, such as RAB3a, was found to accelerate tumor formation and promote tumor cell proliferation by its increased expression level." (PMID 32266223, 2020). "To investigate the potential roles of Rab3A in HCC progression, we first determined Rab3A levels in HCC tissues and observed upregulated mRNA and protein levels of Rab3A in most tumor tissues." (PMID 30237463, 2018). "In summary, we found that despite the upregulation in HCC, Rab3A functions as a tumor suppressor in HCC metastasis and metabolic reprogramming." (PMID 30237463, 2018). "Further IHC assay on 180 pairs of HCC samples also revealed the significant upregulation of Rab3A in HCC tumor tissues (p < 0.001)." (PMID 30237463, 2018). "Further IP analysis on HCC tumor tissues and adjacent normal tissues revealed that Rab3A and O-GlcNAcylation were both increased in HCC tissues, and the O-GlcNAcylation levels of Rab3A was higher in tumor tissues than that in normal ones." (PMID 30237463, 2018). "Higher levels of Rab3A in tumor tissues compared with adjacent normal tissues were determined by qPCR and WB analysis in 16 pairs of HCC tissue samples (p < 0.001)." (PMID 30237463, 2018). "It has been shown that Rab3a promotes tumor initiation and progression, thereby suggesting that Rab3a is involved with cell growth." (PMID 28900422, 2017). "Additionally, high RAB3A expression was significantly correlated with key clinical parameters, including tumor size (p = 0.024) and lymph node metastasis (p = 0.002)." (PMID 41123819, 2025). "Moreover, they investigated the role of this gene in mice models and observed that RAB3A affects tumour initiation, transformation and drug-resistance primarily by inducing cell cycle progression through cyclin D1 stimulation." (PMID 33686173, 2021). "Furthermore, RAB3A is a member of the Ras-associated binding (RAB) family, known to be associated with more aggressive and treatment-refractory tumours." (PMID 33686173, 2021). "Furthermore, due to the common hyper-O-GlcNAcylation in HCC tumor cells, upregulated Rab3A malfunctions in most HCC patients." (PMID 30237463, 2018). "However, different from its oncogenic roles in other neoplasms, Rab3A suppresses metastasis by enhancing OXPHOS in HCC, which is attenuated by the O-GlcNAcylation on Rab3A." (PMID 30237463, 2018). "Therefore, hyper-O-GlcNAcylation in most HCC tumor cells increases the threshold level, and the effects of endogenous Rab3A in HCC cell lines are dampened as revealed in our study." (PMID 30237463, 2018).
tumor (continued). "Further results indicate that RAB3A knockdown promotes BAG6-EP300 into the nucleus, increasing the stability of tumor suppressor genes and inhibiting tumor proliferation." (PMID 41123819, 2025). "Additionally, exposure to CIH in mice engrafted with epithelial lung cancer cells increased tumor size, weight and invasiveness, as well as the shedding of DNA into circulation, which carried epigenetic modifications, such as hypermethylation of the tumor-promoting Rab3a gene." (PMID 31208080, 2019). "Rab3A is upregulated at both the transcript and protein levels in HCC tumor tissue." (PMID 33747521, 2021).
cancer (6 papers, 2010 to 2025). A tumor composed of atypical neoplastic, often pleomorphic cells that invade other tissues. "Further studies on downstream signaling of Rab3A and the effects of O-GlcNAcylation on Rab3A in other cancers are required." (PMID 30237463, 2018). "Both PAR2 and PAR1 activation resulted in up-regulated expression of several genes (CD44, FOSL1, TNFRSF12A, RAB3A, COPEB, CORO1C, THBS1, SDC4) known to be important in cancer." (PMID 21072196, 2010). "RAB3A and PIK3R2 were found to be co-expressed in human cancers." (PMID 41408150, 2025). "Intriguingly, the opposite roles of Rab3A in different cancers and its universal effects on OXPHOS suggest that mitochondrial oxidative metabolism might also play opposite roles in different cancers." (PMID 30237463, 2018). "In addition, we found some hypermethylated genes with an associated decrease in expression, such as ANK3, TSPYL5, RAB3A and ABCA2 that have been reported to be related with cancer or central nervous system diseases." (PMID 29221210, 2017).
infection (4 papers, 2013 to 2024). The state of being infected such as from the introduction of a foreign agent such as serum, vaccine, antigenic substance or organism. "However, the infection of Rab3a-deficient pituitary tissue slice with a GTPase-deficient Rab3a mutant and a mutant deficient in GTP binding resulted in secretory responses not significantly different from those in Rab3a KO cells." (PMID 24205339, 2013). "RAB3A was the most downregulated gene in bovine macrophages 2 h after infection with MAP, likely representing a strategy of MAP to inhibit phagosomal maturation to promote its own intracellular survival." (PMID 30733564, 2019).
brain diseases (1 paper, 2015). "The three genes (AP2A2, CACNG2, and RAB3A) in gene sets of at least two brain diseases were significantly enriched 'synaptic transmission' term of Reactome pathway with Benjamini corrected p-value of 0.022." (PMID 26043779, 2015).
Kidney Disease (1 paper, 2021). "Therefore, this review provides an overview of the relevance of Rab GTPases in human diseases, with a special focus on the Rab3a-Rph3A complex and its critical role in kidney disease and a mention of future implications." (PMID 34299299, 2021).
psychiatric disorder (1 paper, 2023). A disorder characterized by behavioral and/or psychological abnormalities, often accompanied by physical symptoms. "In the PPI network of these Egr targets in the DG region, the top key nodes tightly associated with distinct psychiatric disorders and addictive behaviors in previous studies included Syt1, Stx1a, Dlg4, Cplx1, Gria1, Snap25, Rab3a, and Bdnf81,86–91." (PMID 37758941, 2023).
RAB3A also shares sentences with these, for which no sentence is quoted: autism (2 papers); Lewy body dementia (2); nervous system disorder (2); brain tumors (1); breast carcinoma (1); cardiovascular disease (1); central nervous system diseases (1); depression (1); Diarrhea (1); familial spastic paraplegia (1); Glucose intolerance (1); Hypertension (1); Hypoinsulinemia (1); Intellectual disability (1); lung squamous cell carcinoma (1); metabolic syndrome (1); parasite infections (1); type 1 diabetes mellitus (1).